HMOX1 (heme oxygenase 1)
Diseases named in the same sentence as HMOX1 in open-access papers (continued):
Sharing a sentence is not in itself a finding about the gene and the disease.
urothelial carcinoma (4 papers, 2010 to 2021). A malignant neoplasm derived from the transitional epithelium of the urinary tract (urinary bladder, ureter, urethra, or renal pelvis). "There are significant differences in the distribution of the HMOX1 genotype in patients with different-stage urothelial carcinoma." (PMID 20059769, 2010).
uveal melanoma (4 papers, 2021 to 2024). A melanoma derived from melanocytes of the uveal tract. "Elevated HMOX1 expression was significantly correlated with an unfavorable OS, DSS, and PFI in both uveal melanoma (UVM) and LGG." (PMID 34858984, 2021).
venous thromboembolism (4 papers, 2014 to 2025). Occlusion of the lumen of a vein by a thrombus that has migrated from a distal site via the blood stream. "Subjects with a long promoter for the HMOX1 gene (associated with decreased HO-1 anticoagulant activity) present an increased risk of recurrent venous thromboembolism, whilst HO-1 has been demonstrated to exert a significant antiviral activity against a wide variety of viruses." (PMID 34572292, 2021). "In addition, an association between venous thromboembolism and genetic variation in HO-1 (HMOX1), methylenetetrahydrofolate reductase (MTHFR) C677T polymorphism, affected homocysteine levels, and plasminogen activator inhibitor-1(PAI-1) 4G/5G mutation." (PMID 32549393, 2020). "In addition, participants with genetic variants related to oxidative stress, such as heme oxygenase 1, had a higher risk of recurrent venous thromboembolism." (PMID 24755831, 2014).
acute alcoholic hepatitis (3 papers, 2019 to 2024). "In addition, the serum levels of heme oxygenase-1 (HMOX1) were lower in patients with acute alcoholic hepatitis compared to healthy controls." (PMID 35713687, 2022).
acute promyelocytic leukemia (3 papers, 2018 to 2023). An aggressive form of acute myeloid leukemia (AML), characterized by arrest of leukocyte differentiation at the promyelocyte stage, due to a specific chromosomal translocation t(15;17) in myeloid cells. "In support of this, HTyr has been shown to induce the expression of EGR1 in human promyelocytic leukemia cultured cells and, the oral administration of sulforaphane or SFGluc promoted the appearance of derived metabolites and the induction of HMOX1 in the breast tissue of rats and women." (PMID 29932449, 2018).
AIDS (3 papers, 2014 to 2016). A syndrome resulting from the acquired deficiency of cellular immunity caused by the human immunodeficiency virus (HIV). "For example, KSHV infection induces heme oxygenase-1 (HMOX-1 or HO-1), an inducible enzyme responsible for the rate-limiting step in heme catabolism, in infected endothelial cells and/or AIDS-KS tissues." (PMID 26675551, 2016).
Alpha-thalassemia (3 papers, 2016 to 2024). Alpha-thalassemia is an inherited hemoglobinopathy characterized by impaired synthesis of alpha-globin chains leading to a variable clinical picture depending on the number of affected alleles. "Co-inheritance of alpha-thalassemia also led to a delayed onset of albuminuria in patients (all ages) with HbSS and the presence of at least one C allele of the HMOX1 variant was associated with a decreased cumulative risk of albuminuria in children with HbSS (p = 0.028)." (PMID 38791464, 2024).
autism (3 papers, 2023 to 2025). Persistent deficits in social interaction and communication and interaction as well as a markedly restricted repertoire of activity and interest as well as repetitive patterns of behavior. "In contrast, one study found elevated serum levels of Keap1 and Nrf2 in children with autism along with reduced levels of heme oxygenase-1 (HO-1), a key antioxidant enzyme whose gene expression is regulated by Nrf2." (PMID 40227289, 2025).
bronchiolitis (3 papers, 2023 to 2025). Inflammation of the bronchioles characterized by swelling of the bronchioles and mucus accumulation. "Accordingly, we recently observed a relatively low transcriptional activation of NRF2 and heme oxygenase 1 (HO1) expression in an age‐homogeneous group of hospitalized children affected by respiratory syncytial virus (RSV) severe bronchiolitis." (PMID 39810451, 2025).
cartilage disorders (3 papers, 2022 to 2023). "HMOX1 plays a role in tissue injury and in cartilage disorders, including IVDD." (PMID 37447201, 2023).
chronic hepatitis C (3 papers, 2012 to 2014). "On the other hand, reduced HMOX1 expression has been reported in the liver tissue of patients with chronic hepatitis C; although under in vitro conditions hepatic HMOX1 overexpression in the presence of HCV proteins has been reported by other authors." (PMID 23536765, 2013). "Our results do not support the importance of Bach-1 in repression of HMOX1 in patients with chronic hepatitis C." (PMID 24752012, 2014).
chronic lymphocytic leukemia (3 papers, 2016 to 2024). "Our results demonstrated that overexpression of HMOX1 inhibited proliferation and promoted apoptosis of UVM cells, which was identified the consistent similarities in the roles of the chronic lymphocytic leukemia." (PMID 38767825, 2024).
coronary atherosclerosis (3 papers, 2009 to 2022). Atherosclerosis of the coronary vasculature. "In conclusion, the regulation of the HMOX1 gene may be determined, at least in part, by genetics, and reduced ability to induce HO-1 expression may be involved in the mechanism of coronary atherosclerosis." (PMID 19389234, 2009).
haemolytic anaemia (3 papers, 2014 to 2024). "Human HMOX1 deficiency is a rare autosomal recessive disorder with hallmark features of haemolytic anaemia, inflammation of multiple organs and vasculature, iron deposition, interstitial fibrosis and growth retardation." (PMID 38509740, 2024). "As HMOX1‐deficient patients develop haemolytic anaemia, we investigated erythropoiesis and haemoglobin synthesis in adults at the age of 5 months." (PMID 38509740, 2024). "Humans lacking heme oxygenase 1 (HMOX1) display growth retardation, haemolytic anaemia, and vulnerability to stress; however, cardiac function remains unclear." (PMID 38509740, 2024).
Heat Stroke (3 papers, 2024 to 2026). A condition caused by the failure of body to dissipate heat in an excessively hot environment or during PHYSICAL EXERTION in a hot environment. "This study elucidates the intricate molecular mechanisms underpinning heat stroke-induced liver injury, highlighting the diverse responses of Kupffer cell (KC) subsets and the pivotal role of HMOX-1 in orchestrating ferroptosis in KCs, particularly in KC2, and NLRP3 inflammasome activation." (PMID 39309491, 2024). "In summary, EGR1 emerges as a pivotal regulator of HMOX-1 expression in KC2, orchestrating ferroptosis and NLRP3 inflammasome activation, thereby contributing to liver injury in the context of heat stroke conditions." (PMID 39309491, 2024).
hemophilia A (3 papers, 2020 to 2025). The most common form of hemophilia characterized by spontaneous or prolonged hemorrhages due to factor VIII deficiency. "For instance, IDO1 and HMOX1 have specifically been associated with a lower incidence of FVIII inhibitors in people with hemophilia A." (PMID 41573577, 2025). "In addition, hemophilia A patients with a higher frequency of alleles with large (GT)n repeats (n≥30) within HMOX1 promoter (associated with lesser HO-1 expression), had an increased prevalence of development of inhibitory anti-factor VIII antibodies." (PMID 33057437, 2020).
hyperferritinemia (3 papers, 2005 to 2020). "Here we report a young man with HMOX1 deficiency that had recurrent autoinflammatory episodes marked by fever, hemolysis and hyperferritinemia with pathologic features similar to MAS and HLH." (PMID 33066778, 2020).
inflammatory skin disease (3 papers, 2021 to 2023). Inflammatory skin disorders covers a broad category that includes many conditions ranging in severity, from mild itching to grave medical health complications These disorders are common in people of all ages and races. "With the advancements in specific HMOX1 inducers and CO-releasing molecules, the presented results establish a proof-of-concept for the development of novel treatments for DLE and other inflammatory skin diseases." (PMID 37507892, 2023).
intervertebral disc degeneration (3 papers, 2016 to 2022). "In this study, we investigated the role of heme oxygenase-1 (HO-1) in intervertebral disc degeneration (IDD) by assessing the effects of HO-1 overexpression on IL-1β-induced apoptosis in nucleus pulposus cells (NPCs)." (PMID 32015215, 2020).
Intraventricular hemorrhage (3 papers, 2015 to 2024). Bleeding into the ventricles of the brain. "It was suggested that increased heme oxygenase-1 observed in choroid plexus cells after experimental intraventricular hemorrhage is probably induced in response to the presence of blood in the cerebrospinal fluid." (PMID 33328892, 2020). "Microglial Hmox1 is thought to reduce inflammation after lipopolysaccharide (LPS) exposure and to improve neurorecovery after intraventricular hemorrhage, but the role of microglial Hmox1 in normal brain development is unknown." (PMID 38775708, 2024).
Listeria monocytogenes infection (3 papers, 2011 to 2025). "Similarly, in Listeria monocytogenes infection, TIM3 expression in macrophages limits the phagocytosis of bacteria through interactions with the transcription factor nuclear factor NRF2 and the down-regulation of CD36 and the heme oxygenase 1-IL1β pathway." (PMID 41307843, 2025).
myeloid leukemia (3 papers, 2014 to 2024). A clonal proliferation of myeloid cells and their precursors in the bone marrow, peripheral blood, and spleen. "Heat shock protein 32 (Hsp32), also known as heme oxygenase-1 (HO-1), is a stress-related cytoprotective molecule that is expressed in normal and neoplastic cells, including myeloid leukemias." (PMID 24681707, 2014).
myocarditis (3 papers, 2021 to 2026). Myocarditis is a condition that is characterized by inflammation of the heart muscle (myocardium). "Experimental data revealed that crocin intervention relieved ICI-related myocarditis in a xenotransplanted tumor model of nude mice through regulating the Hpx/nuclear factor erythroid 2-related factor 2 (Nrf2)/heme oxygenase-1 (HO-1) pathway." (PMID 41596558, 2026).
osteonecrosis (3 papers, 2022 to 2025). A none disease characterized by death of bone tissue due to a lack of blood supply. "Quercetin, kaempferol, and cryptotanshinone could promote the osteogenic differentiation of SANFH by upregulating the expression of the COX-2 genes, and quercetin could also upregulate the expression of the HMOX1 gene in steroid-induced osteonecrosis of the femoral head." (PMID 35915795, 2022).
peripheral nerve injury (3 papers, 2018 to 2023). Injury to a peripheral nerve. "This, from the aspect of RNA expression, further supported that miR-494-3p, let-7e-5p, let-7a-5p, and let-7d-5p might regulate LIF and HMOX1 after peripheral nerve injury." (PMID 30558654, 2018).
selenium deficiency (3 papers, 2019 to 2025). A nutritional deficiency disease resulting from inadequate selenium levels in the body, which can lead to impaired function of selenoproteins essential for antioxidant defense and thyroid hormone metabolism. "The activation of NRF2 upon selenium deficiency is discussed to compensate for the loss of antioxidant selenoproteins by upregulating selenium-independent antioxidant proteins such as NQO1, HMOX1, and glutathione transferases." (PMID 39456464, 2024).
spinal cord injury (3 papers, 2015 to 2023). Penetrating and non-penetrating injuries to the spinal cord resulting from traumatic external forces (e.g., WOUNDS, GUNSHOT; WHIPLASH INJURIES; etc.). "An in vivo study conducted on dogs demonstrated that post-spinal cord injury (SCI) transplantation of ADMSCs overexpressing BDNF (BDNF-ADMSC) and ADMSCs overexpressing heme oxygenase-1 (HO1-ADMSC) significantly contributed to functional recovery, inflammation reduction, and restoration." (PMID 38004615, 2023).
Splenomegaly (3 papers, 2015 to 2026). Abnormal increased size of the spleen. "The few surviving Hmox1−/− animals display an inflammatory phenotype characterized by kidney dysfunction, premature death, splenomegaly, and tissue iron deposition." (PMID 41550715, 2026).
tongue cancer (3 papers, 2019 to 2022). A malignant neoplasm affecting the tongue. "Moreover, a unique signature of apoptosis-related proteins, including augmented nuclear factor erythroid 2-related factor 2 (Nrf2)/heme oxygenase-1 (HO-1) expression and caspase activation, was observed in DSK-treated tongue cancer cell lines." (PMID 35806120, 2022).
Zinc deficiency (3 papers, 2024 to 2026). A deficiency of the essential metal Zinc; an essential cofactor for many enzymes. "The universal cytotoxic mechanisms of Cd targeting mitochondria and zinc deficiency are discussed together with the fundamental anti-Cd defenses, involving zinc, de novo heme biosynthesis, and heme oxygenase-1 (HO-1) induction." (PMID 40001486, 2025).
acute porphyria (2 papers, 2015 to 2024). "In addition to its role in the treatment of acute porphyrias, FPR has been found to play an essential protective role in many pathological conditions, including autoimmune disorders, tumor formation, and cardiovascular diseases by inducing Heme Oxygenase-1 (HO-1)." (PMID 39518827, 2024).
age (2 papers, 2022 to 2025). A temporal measurement of the time period elapsed since an identifiable point in the life cycle of an organism. "TAC and TAC/PL treatments reduced expression of Hmox1, and decreased expression of Hmox1 has been associated with age-related impaired memory." (PMID 35216124, 2022).
brucellosis (2 papers, 2015 to 2025). Brucellosis is a bacterial infection that spreads from animals to people via unpasteurized dairy products or by exposure to contaminated animal products or infected animals. "The G protein-coupled receptor (Hrh4), as well as, Mediterranean fever (Mefv), the inducible heme oxygenase-1(Hmox1) and the Neutrophil cytosol factor 1 (Ncf1) were hubs in the network associated with inflammatory responses." (PMID 25902940, 2015).
chronic fatigue syndrome (2 papers, 2015 to 2017). "GUASHA has an immune anti-inflammatory effect due to upregulating the heme oxygenase-1, prolonging the endurance time, enhancing the amount of white blood cells and neutrophils, and reducing muscle pain and chronic fatigue syndrome." (PMID 26120346, 2015). "The GUASHA therapy is beneficial for health care and treatment because it effectively improves microcirculation and skin temperature, and it upregulates heme oxygenase-1 and reduces muscle pain and chronic fatigue syndrome." (PMID 26120346, 2015).
coagulation disorders (2 papers, 2019 to 2022). "In addition to modifications targeting coagulation disorders in xenotransplantation, transgenic pigs expressing antiapoptotic and antiinflammatory proteins, such as human tumor necrosis factor-alpha-induced protein 3 (A20) and human heme oxygenase-1 (HO-1), have been produced." (PMID 32002258, 2019).
complication (2 papers, 2019 to 2025). Any disease or disorder that occurs during the course of, or because of, another disease, treatment, or procedure. "In conclusion, the LL genotype of the HMOX1 gene was associated with ischemic cardiac complications in individuals with T1D in the present study." (PMID 40826355, 2025).
cyst (2 papers, 2015 to 2021). A sac-like closed membranous structure that may be empty or contain fluid or amorphous material. "Therefore, we propose that the Mpkd1-2 locus most likely modulates progression of existing renal cystic disease, rather than initiating new cyst formation, which may be regulated by other factors known to impact cyst number, such as the renoprotective enzyme, heme oxygenase-1." (PMID 26295839, 2015).
diabetic encephalopathy (2 papers, 2025). A brain disease that is characterized by functional impairment of cognition, cerebral signal conduction, neurotransmission and synaptic plasticity, and underlying structural pathology associated with diabetes. "Quercetin supplementation has been shown to alleviate diabetic encephalopathy in rats by upregulating the multifunctional regulator nuclear factor erythroid 2-related factor (Nrf2)/heme oxygenase-1 (HO-1) signaling pathway." (PMID 40806520, 2025).
dmd (2 papers, 2021 to 2022). "Heme oxygenase-1 (HO-1, encoded by Hmox1), a heme-degrading enzyme, may alleviate symptoms of DMD, inter alia, through anti-inflammatory properties." (PMID 35008897, 2021). "To investigate the role of HO-1 in DMD, we generated mdx mice lacking the Hmox1 gene, encoding HO-1, (named as mdx/Hmox1−/−), as described in our previous study." (PMID 35008897, 2021). "In our previous study, we observed that around 3-month-old double knockout animals lacking dystrophin and Hmox1 demonstrate impaired exercise capacity and aggravated DMD pathology in comparison to mdx animals." (PMID 35008897, 2021). "In conclusion, we demonstrated complex, tissue, and age-dependent dysregulation of mitophagic and autophagic markers in DMD mice, which are not affected by the additional lack of Hmox1." (PMID 35008897, 2021). "Even though we did not confirm our hypothesis that “self-eating machinery” is impaired in Hmox1-lacking dystrophic animals, it cannot be excluded that such a situation might be present in DMD patients." (PMID 35008897, 2021).
eosinophilia (2 papers, 2015 to 2022). "w., 5 days) relieved ovalbumin-induced airway inflammation, as evidenced by the reduction of eosinophilia, cytokines (IL-4, IL-5), tumor necrosis factor-α (TNF-α), immunoglobulin E (Ig E) and mucus production by increasing the expression of heme oxygenase-1 (HO-1)." (PMID 35847034, 2022).
frontotemporal lobar degeneration (2 papers, 2015 to 2024). "Increased levels of heme oxygenase-1 (HO-1), a putative marker of oxidative injury, were detected in Pick bodies in Pick's disease patients and neuropil threads and glial inclusions in patients with CBD." (PMID 26576216, 2015).
gallstones (2 papers, 2018 to 2019). Solid crystalline precipitates in the biliary tract, usually formed in the gallbladder, resulting in the condition of cholelithiasis. "In addition, liver tissues from patients with NAFLD with gallstones had increased levels of HIF-1α, HMOX1, and VEGFA mRNAs, compared with livers from patients with NAFLD without gallstones." (PMID 29955245, 2018).
haemophilia (2 papers, 2020 to 2024). "We investigated the association of HFE mutations or HMOX1 polymorphisms affecting iron/heme handling with radiographic joint damage in 252 haemophilia patients (severe and moderate)." (PMID 38392579, 2024). "The potential role of regulators of peripheral tolerance has been recently explored in hemophilia, with a specific focus on two immunoregulatory enzymes: heme oxygenase-1 (HO-1) and indoleamine 2,3 dioxygenase (IDO; IDO-1)." (PMID 32351505, 2020).
Hematuria (2 papers, 2019 to 2021). The presence of blood in the urine. "Envenomed rats presented hematuria, hemoglobin deposition inside proximal and distal tubules and heme-scavenging molecules (such as hemopexin, heme-oxygenase-1 and biliverdin-reductase) was found to be up-regulated in envenomed kidneys." (PMID 30763408, 2019).
hemorrhagic disease (2 papers, 2020 to 2024). Spontaneous or near spontaneous bleeding caused by a defect in clotting mechanisms (blood coagulation disorders) or another abnormality causing a structural flaw in the blood vessels (hemostatic disorders). "More detailed mechanistic insights into the complex pathology of hemolytic/hemorrhagic diseases through heme oxygenase-1/CO as well as H2S pathways would reveal new therapeutic approaches that can be exploited for clinical benefit." (PMID 33374506, 2020).
Hyperammonemia (2 papers, 2017 to 2024). An increased concentration of ammonia in the blood. "Additionally, hyperammonemia in vivo was associated with increased expression and activity of heme oxygenase-1 (HO-1), a ubiquitous marker of oxidative stress." (PMID 35917006, 2024).